SSTR2 (somatostatin receptor 2)
Description:
Receptor for somatostatin-14 and -28. This receptor is coupled via pertussis toxin sensitive G proteins to inhibition of adenylyl cyclase. In addition it stimulates phosphotyrosine phosphatase and PLC via pertussis toxin insensitive as well as sensitive G proteins. Inhibits calcium entry by suppressing voltage-dependent calcium channels. Acts as the functionally dominant somatostatin receptor in pancreatic alpha- and beta-cells where it mediates the inhibitory effect of somatostatin-14 on hormone secretion. Inhibits cell growth through enhancement of MAPK1 and MAPK2 phosphorylation and subsequent up-regulation of CDKN1B. Stimulates neuronal migration and axon outgrowth and may participate in neuron development and maturation during brain development. Mediates negative regulation of insulin receptor signaling through PTPN6. Inactivates SSTR3 receptor function following heterodimerization.
Synonyms: SST2
Tractability: Small molecule: a drug acting on it is in phase 2 or 3 trials; a structure with a bound ligand is known; a high-quality ligand is known; it belongs to a druggable protein family. Antibody: its Gene Ontology location is reachable by antibodies, with high confidence; UniProt places it where antibodies can reach, with medium confidence; UniProt predicts a signal peptide or a membrane-spanning region. PROTAC: a small molecule that binds it is known. Other modalities: an approved drug acts on it.
Target class: Peptide receptor (family A GPCR); Membrane receptor; Short peptide receptor (family A GPCR); Family A G protein-coupled receptor; Somatostatin receptor
Chemical probes: CHEMBL305279, CHEMBL3144285
Gene: Protein-coding gene on chromosome 17 (73,165,010 to 73,176,633, forward strand). Ensembl gene ENSG00000180616.
Subcellular location: Cell membrane; Cytoplasm
Subcellular location (Human Protein Atlas): Cytosol; Nucleoplasm
Pathways (Reactome):
Signal Transduction: G alpha (i) signalling events; Peptide ligand-binding receptors
Gene Ontology:
Molecular function: PDZ domain binding; protein binding; neuropeptide binding; somatostatin receptor activity; G protein-coupled receptor activity
Biological process: cellular response to estradiol stimulus; cellular response to glucocorticoid stimulus; G protein-coupled receptor signaling pathway, coupled to cyclic nucleotide second messenger; negative regulation of cell population proliferation; neuropeptide signaling pathway; G protein-coupled receptor signaling pathway; somatostatin signaling pathway
Cellular component: cytosol; neuron projection; plasma membrane; cytoplasm; membrane
Genetic constraint (gnomAD): Loss-of-function variants: 10 observed, 22.42 expected, observed/expected ratio (o/e) 0.45, 90% interval 0.27 to 0.76. The upper end of that interval is the gene's LOEUF score, 0.76, which puts it in group 3 of 6, group 1 being the genes least tolerant of losing a copy. Missense variants: 364 observed, 494.54 expected, observed/expected ratio (o/e) 0.74, 90% interval 0.68 to 0.8. Synonymous variants: 177 observed, 191.07 expected, observed/expected ratio (o/e) 0.93, 90% interval 0.82 to 1.05.
Homologues: Orthologues: chimpanzee SSTR2 (100% identical), pig SSTR2 (96% identical), mouse Sstr2 (94% identical), guinea pig Sstr2 (93% identical), rat Sstr2 (93% identical), rabbit SSTR2 (93% identical), macaque SSTR2 (91% identical), dog SSTR2 (88% identical), tropical clawed frog sstr2 (84% identical), zebrafish sstr2a (64% identical), zebrafish sstr2b (62% identical), Drosophila melanogaster AstC-R2 (40% identical). Paralogues in human: SSTR5 (49% identical), SSTR3 (47% identical), SSTR1 (46% identical), SSTR4 (44% identical), OPRM1 (36% identical), OPRK1 (35% identical), OPRD1 (34% identical), NPBWR2 (33% identical), OPRL1 (32% identical), NPBWR1 (30% identical), KISS1R (26% identical), CMKLR2 (24% identical), and 5 more.
Diseases named in the same sentence as SSTR2 in open-access papers:
SSTR2 is named in the same sentence as 220 diseases in open-access papers, as found by Europe PMC text mining. Sharing a sentence is not in itself a finding about the gene and the disease. The quoted sentences say what the papers report.
neuroendocrine tumors (128 papers, 2008 to 2026). "These convincing results underline that SSTR2 is significantly and widely present in neuroendocrine tumors." (PMID 39202532, 2024). "Studies have shown that SSTR2 is associated with tumorigenesis in stomach and breast cancer and overexpressed in neuroendocrine tumors." (PMID 37900156, 2023). "SSTR2 expression has previously been associated to improved survival with neuroendocrine tumors and childhood neuroblastomas, suggesting a potential role for SSTR2 as a tumor suppressor." (PMID 25977882, 2015). "A high expression of SSTR2 was associated with longer OS in neuroendocrine tumors (NETs)." (PMID 37185426, 2023). "It is clear that well differentiated neuroendocrine tumors express high levels of SSTR2, but a connection between SSTR2 and pathologic angiogenesis, possibly associated with TEM8/ANTXR1 is only speculation at present." (PMID 36090051, 2022). "[177Lu]Lu-DOTATATE is approved by the European Medicines Agency and the U.S. Food and Drug Administration for the treatment of SSTR2-positive gastroenteropancreatic neuroendocrine tumors based on the results of the phase III NETTER trial." (PMID 40774695, 2026). "In 1994, the FDA approved [111In]In-pentetreotide (OctreoScanTM) as the first somatostatin receptor subtype 2 (SSTR2) targeting radiotracer for SPECT imaging of SSTR2-positive neuroendocrine tumours (NETs)." (PMID 40016527, 2025). "For example, malignant neuroendocrine tumors occasionally show low uptake on somatostatin scintigraphy and high uptake on FDG-PET because of SSTR2 deficiency and high glucose transporter or modified glucose metabolism, respectively." (PMID 39726667, 2025). "Somatostatin receptor 2 (SSTR2) has significant relevance because of its overexpression in certain types of neuroendocrine tumors (NETs)." (PMID 39884771, 2025). "PRRTs, including somatostatin analogs, have been successful for the treatment of neuroendocrine tumors due to the ubiquitous expression of somatostatin receptor 2 (SSTR2)." (PMID 40868217, 2025). "Our data show that SSTR2 antagonists not only had 10-fold higher binding to neuroendocrine tumor cells compared to agonists such as 177Lu-DOTA-TOC or -TATE, but also exhibited increased binding to HSC and MPP compared to the agonists." (PMID 40521188, 2025). "Neuroendocrine tumors are unique in the fact that they express high levels of the somatostatin receptor type 2 (SSTR2), which represents a target for both tumor imaging and therapeutics." (PMID 41040380, 2025). "After confirming the diagnosis of a thymic‐origin neuroendocrine tumor, we assessed somatostatin receptor subtype 2 (SSTR2) expression by immunohistochemistry." (PMID 41394933, 2025). "Based on these results, the U.S. Food and Drug Administration and the European Medicines Agency have approved 177Lu-Oxodotreotide for the treatment of SSTR2-positive gastroenteropancreatic neuroendocrine tumors in patients aged 12 years and older." (PMID 40722619, 2025). "Among these, 177Lu-Oxodotreotide (177Lu-DOTATATE, Lutathera®) is a radioligand therapy (RLT) that facilitates the precision treatment of neuroendocrine neoplasms (NENs) by selectively binding to somatostatin receptor 2 (SSTR2)." (PMID 40722619, 2025). "The tumor displayed moderate membranous staining in more than half of the cells, consistent with reports that approximately 57% of thymic neuroendocrine tumors express SSTR2 and that strong membrane expression is seen in roughly one quarter of cases." (PMID 41394933, 2025). "Somatostatin type 2 receptor (SSTR2) radionuclide therapy using β- particle-emitting radioligands has entered clinical practice for the treatment of neuroendocrine neoplasms (NENs)." (PMID 39310112, 2024). "Some tumors, such as neuroendocrine tumors, express the SSTR2 strongly, which allows a sensitive detection of said tumors and their metastases." (PMID 39123352, 2024).
neuroendocrine tumors (continued). "Somatostatin receptor (SSTR) is overexpressed on the majority of neuroendocrine neoplasms cell surface, and somatostatin receptor subtype 2 (SSTR2) has become an essential target for diagnosis and radionuclide therapy of neuroendocrine neoplasms." (PMID 39479016, 2024). "[68Ga] Ga-DOTA-TATE is a clinically available radiopharmaceutical binding to SSTR2 and widely used for neuroendocrine tumors imaging." (PMID 39225817, 2024). "Since SSTR2 has been found highly expressed in a majority of neuroendocrine neoplasms (NENs), the antitumor activity of SSTR2 has been explored in the treatment of NENs, including PNETs." (PMID 38279330, 2024). "Prospective placebo-controlled and randomized studies have shown that neuroendocrine tumors displaying a stronger SSTR2 expression are more likely to have a favorable prognosis when treated using SSAs." (PMID 39123352, 2024). "Among these, SSTR1 and SSTR2 were found to be consistently expressed in neuroendocrine neoplasms of the gastrointestinal/pancreatobiliary tract, and this discovery has led to revolutionary changes in the diagnosis and management of these tumours." (PMID 39767203, 2024). "Recently, scientists reported a remarkable finding regarding the membrane expression of somatostatin receptor subtype 2 (SSTR2) in neuroendocrine tumor cells, which is increased approximately 20-fold compared to normal cells." (PMID 39202532, 2024). "SSTR2 is a receptor that is often dysregulated in different types of tumors, including neuroendocrine tumors, breast cancer, lung cancer, and prostate cancer." (PMID 37713112, 2024). "Somatostatin receptor 2 (SSTR2) is significantly overexpressed by neuroendocrine tumors (NETs) and is an important target for nuclear imaging and therapy." (PMID 39149492, 2024). "To date, there have been limited reports on the interplay between ncRNAs and SSTR2 signaling in cancers, with the existing literature mainly focusing on neuroendocrine neoplasms." (PMID 38279330, 2024). "While existing vectors for targets such as SSTR2 on neuroendocrine tumors and PSMA on prostate cancer have shown significant promise in theranostic clinical trials, they can still be improved." (PMID 39479448, 2024). "68Ga-DOTANOC has been proposed to be superior to 68Ga-DOTATATE for neuroendocrine tumor imaging due to its broader affinity to SSTR receptors (SSTR2,3,5) that detects more lesions than 68Ga-DOTATATE." (PMID 39038008, 2024). "Comparable IHC staining of SSTR2 between fibrotic myocardium and the neuroendocrine tumor sample used as possible control suggests that the levels of SSTR2 in ICM samples would be sufficient to be visible by PET, however, this was not directly tested." (PMID 39038008, 2024). "[177Lu]Lu-DOTATATE (Lutathera®) has been approved for the treatment of somatostatin receptor 2 (SSTR2) positive neuroendocrine tumours (NETs) by both EMA and FDA." (PMID 37823909, 2024). "The level of Sstr2 expression in neuroendocrine tumors is a limiting factor in the use of Sstr2 agonists or theranostics in neuroendocrine tumor patients." (PMID 36965619, 2023). "Sstr2 is a Gi-coupled receptor that inhibits cAMP production, which is critical to its ability to suppress excess hormone secretion in neuroendocrine tumors." (PMID 36965619, 2023). "As a result, approaches to promote cell surface expression of Sstr2 in neuroendocrine tumor cells would be impactful." (PMID 36965619, 2023). "Several targets are of clear interest, such as prostate-specific membrane antigen (PSMA) in prostate cancer and somatostatin receptor 2 (SSTR2) in neuroendocrine tumors." (PMID 37511386, 2023). "In this study, we investigated the interactionof six radiopharmaceuticalswith SSTR2, a key drug target for neuroendocrine tumors." (PMID 37466559, 2023). "PRRT with octreotide aims to selectively irradiate somatostatin receptor 2 (SSTR2)-expressing neuroendocrine tumor cells and the surrounding blood vessels to inhibit the angiogenetic response during treatment." (PMID 37258584, 2023).
neuroendocrine tumors (continued). "SSTR2, a G protein coupled cell surface receptor, inhibits cell proliferation, and is mainly expressed in neuroendocrine tumors." (PMID 37318724, 2023). "We observed a strong downregulation of Sstr2 expression in the Wnt7a expressing cells, indicating that Wnt signaling is also capable of downregulating endogenous Sstr2 expression in neuroendocrine tumor cells." (PMID 36965619, 2023). "In another study, docking was performed by the Tripos Surflex-Dock module with different binding poses of a selected ligand and SSTR2, one of the five subtypes of somatostatin receptors overexpressed in many neuroendocrine tumors." (PMID 37047831, 2023). "The isoform 2 (SSTR2) is of particular relevance for the therapy of neuroendocrine tumours for which different analogues to somatostatin are currently in clinical use." (PMID 36959237, 2023). "High Sstr2 expression is also a defining feature in many neuroendocrine tumors, and as such Sstr2 agonists are often used to suppress the excess hormone secretion that is a common, debilitating feature in these tumors." (PMID 36965619, 2023). "Intervention in this signaling mechanism has the potential to elevate Sstr2 expression in neuroendocrine tumors and enhance Sstr2-directed therapies." (PMID 36965619, 2023). "The Somatostatin receptor 2 (Sstr2) is a heterotrimeric G protein-coupled receptor that is highly expressed in neuroendocrine tumors and is a common pharmacological target for intervention." (PMID 36965619, 2023). "Somatostatin receptor 2 (SSTR2) is highly expressed in neuroendocrine tumors and represents as a therapeutic target." (PMID 36810324, 2023). "In neuroendocrine tumor cells, the SSTR2 agonist octreotide reduced intracellular levels of VEGF by decreasing HIF-1α cell content." (PMID 36946182, 2023). "Two SST14-derived short cyclic SST analogues (lanreotide or octreotide) with improved stability and longer lifetime were developed as drugs to preferentially activate SSTR2 and treat acromegalia and neuroendocrine tumors." (PMID 35595746, 2022). "SSTR2 has been widely recognized as an attractive target for imaging and treatment of patients with benign and malignant neuroendocrine tumors (NETs)." (PMID 35962347, 2022). "Sstr2, anti-Sstr2 antibody drugs and Sst-image have been developed for diagnosis and therapy in pituitary and neuroendocrine tumors; signaling-mediated plasma membrane resurfacing of Sstr2 can fine-tune pituitary hormone release." (PMID 36147561, 2022). "177Lu-DOTATATE treatment targets tumor cells overexpressing the somatostatin receptor type 2 (SSTR2) and is authorized in Europe and the United States as Lutathera (Advanced Accelerator Applications) for therapy of metastasized neuroendocrine tumors." (PMID 34503959, 2022). "Neuroendocrine tumors (NETs) expressing the somatostatin receptor subtype 2 (SSTR2) are promising targets for peptide receptor radionuclide therapy (PRRT) using the somatostatin analogue Lu-177-DOTATATE." (PMID 35626117, 2022). "Targeted radionuclide therapy using β-emitting radiolabeled somatostatin analogs is currently applied to patients bearing inoperable neuroendocrine tumors that overexpress the somatostatin receptor type 2 (SSTR2)." (PMID 33837068, 2022). "Somatostatin receptor 2 (SSTR2) was the object of efforts to develop new ligands for treating neuroendocrine tumors (NETs)." (PMID 35892711, 2022). "Somatostatin receptor subtype 2 (SSTR2) has become an essential target for radionuclide therapy of neuroendocrine tumors (NETs)." (PMID 36145375, 2022). "Somatostatin receptor 2 (SSTR2) has been shown to be expressed in a subset of neuroendocrine tumors and carcinomas and plays a role in imaging studies and guiding therapy." (PMID 35198446, 2022). "Somatostatin receptor subtype 2 (SSTR2) is present at a high incidence in neuroendocrine tumors (NETs) and therefore is an ideal target for imaging and therapy of this malignant disease." (PMID 36145375, 2022).
neuroendocrine tumors (continued). "Accordingly, SSTR2 is an important drug target for the treatment of multiple diseases, such as neuroendocrine tumors (NETs), thyrotropinoma, and cancer." (PMID 35595746, 2022). "Treatment of neuroendocrine tumors (NETs) largely depends on radioligands targeting somatostatin receptor type 2 (SSTR2)." (PMID 36145375, 2022). "It has been used for over a decade to diagnose rare neuroendocrine tumors, since this neoplasm commonly has a high expression of SSTR2." (PMID 35890111, 2022). "SSTR2 is an important target in well differentiated neuroendocrine tumors which have high expression of this receptor." (PMID 36090051, 2022). "Such a theranostic approach has only been clinically approved so far for neuroendocrine tumor therapy and is in late-stage clinical trials for prostate cancer, using agents targeting the SSTR2 and the Prostate Specific Membrane Antigen (PSMA), respectively." (PMID 33916607, 2021). "The introduction of somatostatin analogues (SSA) was a major therapeutic advance in the management of well-differentiated neuroendocrine tumors with good somatostatin receptors type 2 (SSTR2) expression." (PMID 34946232, 2021). "One of the first reports regarding HDACi action in neuroendocrine tumors showed an increase in SSTR2 expression in Bon-1 and QGP1 cells." (PMID 34204116, 2021). "Loss of Somatostatin Receptor 2 (SSTR2) expression and rising CXC Chemokine Receptor Type 4 (CXCR4) expression are associated with dedifferentiation in neuroendocrine tumors (NET)." (PMID 33671498, 2021). "The increased density of somatostatin type 2 receptors (SSTR2) in neuroendocrine tumors allows for peptide receptor radionuclide therapy." (PMID 33494435, 2021). "In particular, SSTR2 is highly expressed by neuroendocrine tumors such as gastroenteropancreatic neuroendocrine tumors, pheochromocytoma/paragangliomas, and most neuroblastomas (60–90%)." (PMID 33916640, 2021). "The FDA-approved 68Ga-DOTATATE (NETSPOTTM) for somatostatin receptor 2 (SSTR2) positive neuroendocrine tumors (NETs) has been long suggested to diagnose PCa patients with NED." (PMID 34884893, 2021). "[68Ga]Ga-DOTA-TATE is a selective radiopharmaceutical binding to somatostatin receptors subtype-2 (SSTR-2) that has been developed in the field of oncology, especially in neuroendocrine tumors with higher performance compared to other radiopharmaceuticals." (PMID 34885690, 2021). "68Ga-labelled peptides targeting somatostatin receptor 2 (SSTR2) have demonstrated encouraging results in managing patients with neuroendocrine tumours (NETs)." (PMID 32297029, 2020). "Although the subject numbers were limited, further investigation of 68Ga-NOTA-TATE is warranted for detecting SSTR2-positive neuroendocrine tumours." (PMID 32297029, 2020). "Peptide receptor radionuclide therapy (PRRT) is an important treatment option for patients with somatostatin receptor-2 (SSTR2)-expressing neuroendocrine tumour (NET) though tumour regression occurs in only a minority of patients." (PMID 32576907, 2020). "As a proof of concept, the purified 47Sc was used to radiolabel DOTATOC, a somatostatin analog that when radiolabeled can be used for diagnosis and therapy of neuroendocrine tumors that overexpress SSTR2." (PMID 31098710, 2019). "In particular, imaging of neuroendocrine tumors exhibiting overexpression of somatostatin receptor type 2 (SSTR2) was promisingly demonstrated in some clinical and preclinical studies with somatostatine analogues." (PMID 30036947, 2018). "Octreotide, which is used to treat patients with acromegaly or neuroendocrine tumors, has higher affinity for SSTR2." (PMID 27966451, 2017). "SSTR2 is a cell surface receptor overexpressed in neuroendocrine tumors and peptide-based SSTR2-targeting, for example by radiolabeled DOTATATE, is already used for diagnostic imaging." (PMID 28542563, 2017). "213Bi-DOTATATE therefore held great promise for targeted therapy for neuroendocrine tumours that express SSTR2." (PMID 26791386, 2016).